ERBB3 (erb-b2 receptor tyrosine kinase 3)
Diseases named in the same sentence as ERBB3 in open-access papers (continued):
Sharing a sentence is not in itself a finding about the gene and the disease.
tumor (continued). "Our RT-PCR analysis of these regions showed an increased expression of ERBB3 in tumor tissues compared to normal tissues in both cases." (PMID 38276060, 2024). "Neuregulin 1 (NRG1) gene is a rare oncogenic driver that can lead to activation of human epidermal growth factor receptor 3 (Her3/ErbB3) mediated pathway, resulting in tumor formation." (PMID 38880928, 2024). "This is particularly significant in kidney disease, where ERBB3’s role in key signaling pathways influences cell survival and proliferation, contributing to tumor growth." (PMID 38276060, 2024). "In GBM, ERBB3, IGFR1R and TGFBR2 were positively correlated with PDGFR, and combining a PDGFR inhibitor with either an ERBB3 inhibitor or an IGF1R inhibitor resulted in a more significant reduction in tumour growth than each inhibitor alone." (PMID 39272879, 2024). "For the AREG and ERBB3 signaling pathway, there was expression of AREG across all the cell types and datasets, supporting its role in signaling to ERBB3, which is expressed exclusively in the tumor epithelial cells." (PMID 38183074, 2024). "UHRF2 has also been reported to affect certain phenotypes of tumor cells through DNA demethylation, the ErbB3/Ras/Raf signaling pathway, and the Wnt/β-catenin signaling pathway." (PMID 38879525, 2024). "The expression patterns and functions of these ERBB3 isoforms can vary greatly, potentially impacting the tumor behavior, response to therapy, and interaction with the tumor microenvironment." (PMID 38276060, 2024). "During a Phase II clinical trial (CRESTONE trial, NCT04383210), this anti-ERBB3 IgG2 monoclonal antibody produced an ORR of 33% across various tumor types harboring NRG1 fusions." (PMID 39575425, 2024). "RT-PCR analysis targeting the exon 21–23 and exon 23 regions of ERBB3 confirmed its heightened expression in tumor tissues, underscoring the significance of alternative splicing and exon utilization in cancer development." (PMID 38276060, 2024). "Mutation of ERBB2/ERBB3 results in an abnormal activation of ERBB signaling pathway and promotes tumor proliferation and metastasis, which can be inhibited by regorafenib." (PMID 37681031, 2023). "Studies have shown that seribantumab, a monoclonal antibody targeting the ligand binding domain of ErbB3, inhibits ErbB3 signaling and tumor growth when a HRG1 autocrine loop is present." (PMID 37316561, 2023). "Comparison of BlCa cells and tumor lines with varying sensitivity to cisplatin demonstrated that cisplatin induced a transient increase in ErbB3 phosphorylation at Y1328, ERK1/2 phosphorylation at T202/Y204, and Akt phosphorylation at S473." (PMID 37316561, 2023). "Inhibition of HRG1 binding to its receptor, and ErbB3 activation, with seribantumab, reduced tumor growth in immunocompromised mice bearing patient-derived xenograft (PDX) tumors that expressed high HRG1 levels and an activated HER2/ErbB3 axis." (PMID 37316561, 2023). "The subcellular localization of ERBB3 in tumor cells was investigated using ICC-IF and confocal microscopy techniques." (PMID 38144565, 2023). "In breast cancer, ErbB3 expression appears to promote tumor growth, whereas ErbB4 expression appears to perform as a weak tumor suppressor." (PMID 36768973, 2023). "Our data shows that under conditions of high HRG1 and active ErbB3, ErbB3 inhibition reduces BlCa tumor growth." (PMID 37316561, 2023). "We found that MAPK14 was highly expressed in 5 of 24 tumor tissues (STAD, CHOL, ESCA, HNSC and LIHC), and ERBB3 is highly expressed in 10 of 24 tumor tissues including STAD." (PMID 37537191, 2023). "HPK uses the human epidermal growth factor receptor ErbB3 (HER3) to target bioparticles to tumor cells and induce tumor cell entry." (PMID 37370850, 2023).
tumor (continued). "ErbBs are variably expressed in different tumours; ErbB1 and ErbB2 subtypes are the most over expressed in tumours, whereas the ErbB3 and ErbB4 are the least expressed." (PMID 38203605, 2023). "Initially, the GDSC database indicated that ERBB3 serves as a biomarker for the sensitivity of these anti-tumor drugs." (PMID 38144565, 2023). "Using additional matched tumor pair analysis, mutations in TRAF7, ARID1A, and ERBB3 were identified as subclonal driver events at the time of recurrence." (PMID 38073632, 2023). "Based on the TCGA database, we plotted a box diagram of MAPK14 and ERBB3 expression for tumor tissues and adjacent normal samples." (PMID 37537191, 2023). "Tumor cells that overexpress ErbB2 exhibit uncontrolled proliferation due to ligand-independent heterodimerization of ErbB2 and ErbB3 and the activation of downstream intracellular phosphoinositide-3-kinase (PIK3) and Akt signaling pathways." (PMID 38132657, 2023). "In mouse models of intestinal tumorigenesis, deletion of Erbb2 and Erbb3 has been reported to both increase and decrease the tumor burden, depending on the genetic background." (PMID 36912192, 2023). "We further discovered, via the CTD database, that 7 anti-tumor drugs have the potential to interact with ERBB3 and impact its gene expression levels." (PMID 38144565, 2023). "ROC analysis has identified ERBB3 as a diagnostic marker for THCA (AUC=0.89), THCA with high LNM potential (AUC=0.75), and lymph nodes with tumor metastasis (AUC=0.86)." (PMID 38144565, 2023). "Tumor driver gene mutations and wild-type samples used for KM analysis showed better survival outcomes in samples with CSMD1 and ERBB3 wildtype compared to samples with CSMD1 and ERBB3 mutations." (PMID 37063290, 2023). "It is found that the high expression of ERBB3 in tumor tissues is consistent with the high expression of ERBB2." (PMID 35581263, 2022). "ERBB3 methylation is closely related to a variety of immune cells and factors in the tumor microenvironment, especially tumor-infiltrating lymphocytes." (PMID 35581263, 2022). "GO and KEGG analysis confirm ERBB3 Methylation were involved in regulating RNA splicing, RNA stability, and cell proliferation create Tumor and immune system interaction, which integrates multiple heterogeneous data types." (PMID 35581263, 2022). "Among the 10 single N-glycan deletion mutants of ErbB3, the ErbB3 N418Q mutant forms a heterodimer with ErbB2 without ligand stimulation, exerts downstream signaling and promotes tumor formation in athymic mice." (PMID 35089466, 2022). "Well-known tumor-related genes were found in this ranking, such as ERBB3 (24th rank), VEGFA (75th rank), and ERBB2 (365th rank)." (PMID 35626066, 2022). "In 18%–29% of cases, the high expression of ERBB3 was positively correlated with metastasis, tumor size, in situ recurrence, tumor grade, and tumor recurrence." (PMID 35990843, 2022). "A marked decrease in ErbB3 expression was detected in the dAd/shErbB3-treated tumors compared with PBS- or dAd-treated tumor tissues." (PMID 35806132, 2022). "In order to verify the mechanism of enhanced antitumor effect and survival benefits of ErbB3 downregulation via the Ad vector, tumor tissues were excised and subjected to histological staining." (PMID 35806132, 2022). "A comprehensive assessment of the ERBB3 multi-omics will help to enhance our understanding of the characteristics of cell infiltration in CESC tumor microenvironment and guide more effective immunotherapy strategies." (PMID 35581263, 2022). "Together, these results demonstrate that oAd/shErbB3 exerted potent antitumor efficacy via robust inhibition of ErbB3 expression and inhibition of tumor cell proliferation, and enhanced induction of apoptosis in the tumor tissues." (PMID 35806132, 2022). "Infigratinib-resistant tumours exhibited higher levels of p-ErbB2 and p-ErbB3, concomitant with an increase in EZH2 expression." (PMID 34156519, 2021).
tumor (continued). "CDX-3379, an anti-ErbB3 monoclonal antibody, has been recently reported to inhibit tumor ErbB3 phosphorylation in HNSCC and induce measurable tumor regression and was well tolerated." (PMID 33718169, 2021). "Unfortunately, tumour DNA from formalin-fixed paraffin-embedded (FFPE) samples was too degraded for massively parallel sequencing, precluding comprehensive assessment of ERBB3 somatic variants." (PMID 34274969, 2021). "On a mixed C57BL/6J and 129S1/SvImJ genetic background (B6;129), we showed that ERBB3 is essential for tumor development." (PMID 34843459, 2021). "Generally, an upward trend was observed in the mRNA levels of total EGFR, ErbB2, and ErbB3 from the PDX tumours treated with infigratinib." (PMID 34156519, 2021). "ERBB3 (Erb-b2 receptor tyrosine kinase 3), as a member of the ErbB family, is highly expressed in a variety of common tumors and can induce resistance to a variety of tumor therapeutic drugs when activated." (PMID 34321959, 2021). "The three novel MET, FGFR4, and ERBB3 isoforms were predicted to be initiated from promoters distinct from their annotated TSSs (51 kb away (MET), 438 bp (FGFR4), 248 bp (ERBB3), and upregulated in tumor samples to a greater degree from their known isoforms." (PMID 33482911, 2021). "MiR‐22 has also been found to target many genes encoding cancer‐associated proteins, including the TET2 tumor suppressor, HDAC6, ERBB3, CDC25C, EVI‐1, and P21, which play different roles in different types of cancer." (PMID 33159388, 2021). "Similar to the previous study on a B6;129 mixed genetic background, a higher number of apoptotic cells were detected in ERBB3-deficient polyps from C57BL/6J-ApcMin/+ mice demonstrating an important role for ERBB3 in tumor cell survival." (PMID 34843459, 2021). "At multivariate Cox regression analysis adjusted for age, liver function (Child–Pugh score) and tumor stage (BCLC), ERBB3 ≥ 2860 resulted significantly and independently associated with OS (HR = 2.24, 95% CI 1.16–4.35, p = 0.017)." (PMID 33799723, 2021). "In our study of tumor recurrence, a significant correlation with RFS was observed in gene mutations (ATR, ERBB3, KDR, and MUC6) and fusions (GOPC-ROS1 and NTRK1-SH2D2A)." (PMID 34599262, 2021). "A previous study displayed that NRG1 exerted its roles in tumors by binding to ERBB2 or ERBB3, resulting in tumor cell proliferation, invasion, and migration." (PMID 34531912, 2021). "Lastly, ERBB3 and SMAD4 mutated tumors had a significantly higher infiltration of mDCs in the tumor and stromal compartments, and RNF43 mutated tumors had a significantly higher infiltration of iDCs in the tumor compartment." (PMID 33013928, 2020). "Co-treatment with both anti-ErbB3 and anti-Trop2 antibodies leads to a greater anti-tumor response than either antibody alone." (PMID 33187148, 2020). "Clinical trials have demonstrated that the migration and in vitro tumor formation of cancer cells that overexpress PARK7 are significantly reduced following treatment with anti-ERBB3 antibodies." (PMID 32357493, 2020). "The released extracellular domain of NRG-1 then activates ErbB3, promoting cell proliferation and tumor growth." (PMID 33187148, 2020). "Epidermal growth factor receptor family members such as ErbB1 and ErbB3 are involved in tumor progression and metastasis." (PMID 30621788, 2019). "The logistic regression model also showed that the ErbB1/ErbB3 over expression, lymph node involvement, and size of tumor were independent prognostic factors." (PMID 30621788, 2019). "ErbB1 mRNA over expression was also significantly correlated with ErbB3 protein expression (p = 0.045), tumor differentiation (p = 0.048), and recurrence (p = 0.026)." (PMID 30621788, 2019). "ErbB3 mRNA over expression was significantly correlated with tumor differentiation (p < 0.05), lymph node involvement (p = 0.001), stage of tumor (p < 0.05), and recurrence (p < 0.05)." (PMID 30621788, 2019).
tumor (continued). "ErbB3 is also involved in the development of resistance by tumour cells to conventional anti-EGFR and anti-ErbB2 therapies." (PMID 31557826, 2019). "In the DNET, considered as a benign grade I tumour, we found high expression levels of ErbB3, FGFR2, FOLH1 and AXL." (PMID 31747973, 2019). "MSI tumours are characterised by MutL homologue 1 (MLH1) silencing and a high mutation burden in genes as PIK3CA and receptor tyrosine protein kinase (ERBB3/HER3)." (PMID 31235864, 2019). "There were significant correlations between ErbB1/ErbB3 co-overexpression and tumor size (p = 0.026), macroscopic features (p < 0.05), tumor differentiation (p < 0.05), stage of tumor (p < 0.05), and recurrence (p < 0.05)." (PMID 30621788, 2019). "In other cases NRG1 was shown to be produced by the same tumour cells and to induce ErbB3 phosphorylation via an autocrine lop." (PMID 31557826, 2019). "Multivariate and logistic regression analyses were also done to assess the roles of ErbB1 and ErbB3 in tumor prognosis and survival." (PMID 30621788, 2019). "Istiratumab monotherapy led to tumor stasis, whereas the combination of dual IGF-1R/ErbB3 inhibition with chemotherapy resulted in tumor regression for all three combinations." (PMID 31728045, 2019). "Metastatic CMM tumors displayed moderate to high cytoplasmic and membranous ERBB3 and MET expression in 12/13 (92%) and 9/21 (43%) BRAF-mutated tumor samples, respectively." (PMID 31506424, 2019). "There was also a significant correlation between tumor size and ErbB3/1 over expression in the level of protein in which the over expressed tumors were smaller than tumors with normal expression (4.25 ± 0.854 vs. 5.14 ± 0.382 cm)." (PMID 30621788, 2019). "For example, a study of the activity of ErbB3 demonstrated the importance of the tumor microenvironment." (PMID 31615015, 2019). "Following on this work, in this report we use a panel of patient-derived xenograft models (PDX) and their cellular derivatives (conditionally reprogrammed cells, or CRCs38) to show that ErbB3 is an essential component of the tumor growth machinery in HNSCC." (PMID 29305574, 2018). "Collectively, these data point to ErbB3 as a mediator of signaling required for survival in the hostile tumor microenvironment, a requirement that is a likely source of the anti-tumor activity of anti-ErbB3 antibodies." (PMID 29305574, 2018). "ERBB3 has been reported as highly expressed in TGCT tumours with signal activation dependent on ERBB2 activation with which it forms heterodimers." (PMID 29160922, 2018). "Taken as a whole, our data suggest that NRG1 in tumor cells, and ErbB3 and JAG1 in macrophages can play an important role in the metastatic cascade." (PMID 29636067, 2018). "Therapeutic targeting of ErbB3 in pre-clinical experiments also reveals equivocal results in terms of the anti-tumor and anti-proliferative efficacy of ErbB3 blockade." (PMID 29305574, 2018). "While ErbB3 inhibition alone exerts potent anti-tumor activity, some “persister” cells are able to survive and show upregulation of Trop2, the negative regulator of ErbB342." (PMID 29305574, 2018). "We found that reducing NRG1 in the tumor cells reduced the ability of macrophages to stimulate iTEM, consistent with a model where NRG1 produced by tumor cells stimulates macrophages through ErbB3." (PMID 29636067, 2018). "In summary, NRG1 was most highly expressed by the tumor cells, while the receptor ErbB3 was mainly present on the surface of macrophages." (PMID 29636067, 2018). "Given the importance of ErbB3 in cancer, an understanding of its organization and dynamics in the plasma membrane of tumor cells is critical." (PMID 29361123, 2018). "We harvested cells from residual tumor nodules from mice treated with ErbB3 antibody for five weeks and measured levels of activated EGFR in residual tumor cells (i.e., persister cells)." (PMID 29305574, 2018).
tumor (continued). "In this study, we show that ErbB3 is essential for tumor growth of treatment-naive HNSCC patient-derived xenografts." (PMID 29305574, 2018). "Our data suggest, however, that ErbB3 is an essential component of the tumor growth machinery in HNSCC and the molecular details provided in this report offer some insight into why this is the case." (PMID 29305574, 2018). "This lack of in vitro efficacy with concomitant in vivo activity led us to consider a role for ErbB3 in responding to the tumor microenvironment." (PMID 29305574, 2018). "Co-treatment with anti-ErbB3 and anti-Trop2 antibodies is synergistic and produces a greater anti-tumor response than either antibody alone." (PMID 29305574, 2018). "Most obvious was the influence on activity uptake in blood, tumours, excretory organs (kidney and liver), and organs with endogenous expression of murine ErbB3 (particularly the liver)." (PMID 30314301, 2018). "In tumor material successfully obtained from ErbB3-treated persister cells from two PDX models, resistance to ErbB3 treatment was associated with an increase in Trop2 protein expression." (PMID 29305574, 2018). "The tumor cells were implanted in mice (n = 5 tumors), allowed to grow to 150 mm3 and treated with the antibody to ErbB3." (PMID 29305574, 2018). "In particular, the ErbB2/ErbB3 heterodimer appears to be important for tumor cell proliferation in certain breast cancers." (PMID 29361123, 2018). "In the mouse xenograft model, SOX10 knockdown also blocked FOXD3/ERBB3 induction by Vemurafenib, reduced tumor growth and further enhanced the tumor-inhibiting capacity of Vemurafenib." (PMID 29295999, 2018). "In each case, we sought to understand if ErbB3 signaling is a potential mechanism promoting drug tolerance and asked if ErbB3 inhibition enables tumor cells to respond to these agents." (PMID 28725482, 2017). "We sought to understand which factors would influence the ability of ErbB3-targeting antibodies to show anti-tumor properties in the potential treatment of HNSCC using KTN3379." (PMID 28723928, 2017). "EGCG was proved to inhibit the tumor growth and the activation of ErbB1, ErbB2, and ErbB3 which are expressed in many different human cancer lines." (PMID 28286519, 2017). "Several genomic regions were preferentially amplified or deleted in tumours harbouring IDC, including gain of BCL6 and loss of MTOR, along with gains of a region harbouring CDK2 and ERBB3." (PMID 28067867, 2017). "ErbB3 predominantly forms a heterodimer with ErbB2 and was found to be critically involved in tumour initiation and progression and is now considered one of the most active signalling dimers of the ErbB family in cancer." (PMID 28417948, 2017). "Using the VeraTag proximity-based immunoassay we observed widespread ErbB3 protein (H3T) expression in the same patient tumor cohort analyzed for NRG1." (PMID 28723928, 2017). "ERBB2, ERBB3 and SYK were functionally more active overall in tumors and TYRO3 was more active in paired tumor samples and also mutated on kinase gene sequencing." (PMID 28423512, 2017). "Overall, the results showed that mir-152-3p induced an anti-tumor effect by negatively regulating ERBB3." (PMID 28570571, 2017). "Together, our data support the clinical evaluation of KTN3379 in HNSCC and provides a scientific rationale that supports the combination of EGFR and ErbB3-targeting mAbs for the treatment of this tumor type." (PMID 28723928, 2017). "Experiments results showed that mir-152-3p acted as an anti-tumor miRNA by negatively regulating ERBB3." (PMID 28570571, 2017). "Some miRNAs have been reported to have an anti-tumor effect that involved negative regulation ERBB3." (PMID 28570571, 2017). "In preclinical experiments, we found that the degree of tumor growth rate inhibition by seribantumab correlated linearly with basal levels of p-ErbB3 measured in tumors of mouse xenograft models." (PMID 28725482, 2017).